STAT1 (signal transducer and activator of transcription 1)
Diseases named in the same sentence as STAT1 in open-access papers (continued):
Sharing a sentence is not in itself a finding about the gene and the disease.
melanoma (continued). "NO inhibits antigen presentation from DCs to CD4+ T cells in the presence of MDSCs in melanoma cells, and nitrated STAT1 can be found in melanoma specimens." (PMID 33255891, 2020). "A mechanism of immune inhibition by MDSC in melanoma was proposed that involves secretion of NO by MDSCs and decreased p-STAT1 signaling in response to IFN signaling." (PMID 33255891, 2020). "Increased CD8+ T-cell infiltration/proliferation, PD-1, PD-L1, granzyme B, and phosphorylated STAT1 positive immune cells in melanoma tumors have been observed by IHC or gene expression after treatment with pembrolizumab or nivolumab in other trials." (PMID 31439037, 2019). "Consistent with previous reports, STAT1 was reported to induce immunogenicity in head and neck cancer, and silencing of STAT1 expression led to immune evasion in melanoma cells." (PMID 30847026, 2019). "It has been reported in the literature that in A375 melanoma cells, Osm can upregulate P27 through a STAT1-dependent cellular pathway to inhibit cell proliferation." (PMID 31358059, 2019). "The differential IFN-γ-induced PD-L1 expression and STAT1 activation were examined in curcumin and apigenin-treated melanoma cells using immunoblotting or immunofluorescence assays." (PMID 30373602, 2018). "In a mouse model for metastatic melanoma, STAT1 knockdown impaired metastatic behavior of the cancer cells and, in melanoma cultured cells, this knockdown decreased the migration and invasive capacity of cancer cells." (PMID 30166456, 2018). "In all 3 melanoma cell lines, apigenin led to a greater suppression of the phosphorylation of STAT1 compared to curcumin, which was in good correlation with the stronger effect of apigenin observed on the downregulation of PD-L1 expression." (PMID 30373602, 2018). "In the present study, we demonstrated that the flavonoid apigenin strongly suppressed the IFN-γ-induced activation of STAT1, leading to decreased expression levels of PD-L1 in melanoma cells and thus rendering them more sensitive to T cell-mediated killings." (PMID 30373602, 2018). "Our results agree with previous observations of the presence of constitutive activation of SRC and STAT1, 3, and 5 proteins in melanoma tumors." (PMID 28223541, 2017). "Afterwards, PBMC derived from the peripheral blood of 8 melanoma patients, 8 pancreatic cancer patients, and 9 normal donors were prepared for a nitrated STAT1 quantification experiment." (PMID 29133913, 2017). "The ratio of [nSTAT1]/[STAT1] was increased in cancer patients (0.30 ± 0.24; melanoma and pancreatic cancer) as compared to normal controls (0.14 ± 0.04, p = 0.036, T test)." (PMID 29133913, 2017). "The distinct upregulation of the basal STAT1 phosphorylation levels, agrees with and puts forth GH action to explain observations in recurrent melanoma phenotypes." (PMID 28223541, 2017). "A recent study reported that both tyrosine phosphorylation of signal transducer and activator of transcription 5 (STAT5) and STAT1 in response to IL-2 stimulation were impaired in melanoma patients and this was correlated with increasing clinical stage." (PMID 27153543, 2016). "Upon intravenous injection of B16F10 melanoma cells, Stat1-Y701F mice developed only few pulmonary tumor nodules by day 14, whereas Stat1−/− mice already showed pronounced signs of tumor burden." (PMID 27757297, 2016). "Yoshimoto proposed that IL-27 had an antiproliferative effect on melanomas through WSX-1/STAT1 signalling." (PMID 26932661, 2016). "It has been shown that STAT1 phosphorylation was significantly decreased in melanoma patients compared with healthy controls when stimulated with IFN-α." (PMID 27153543, 2016). "From these results, we conclude that the suppression of MHC II on the cell surface of these MET melanoma cell lines is due to silencing of STAT1." (PMID 25690042, 2015). "VGP lesions show a further decrease in STAT1 expression, which correlates with an increase in melanoma biomarker expression." (PMID 25690042, 2015).
melanoma (continued). "IFNγ inhibited melanoma cell growth in vitro probably via IFNγ-induced JAK/STAT1 signaling pathway activation." (PMID 25428727, 2014). "While HDACi block IFN-dependent STAT1 signaling, STAT1 expression is increased in melanoma and other solid cancer-derived cells when they are incubated with HDACi." (PMID 24810717, 2014). "Nevertheless, we are aware of a relatively small number of published studies that had found prognostic significance of STAT1 in other types of cancer, such as gastric cancer and melanoma." (PMID 25355139, 2014). "STAT1 restricts cell growth and mediates the antitumor effects of IFN-α, while STAT3 is associated with melanoma tumor progression and host immunosuppression." (PMID 24516470, 2014). "For example, constitutively expressed GILT was negative regulated by STAT1 in fibroblasts, while in melanoma, it was induced directly by STAT1 in IFN-γ-inducible expression way." (PMID 25333930, 2014). "We demonstrated that IFNγ secreted by GM-ADSCs is able to directly affect melanoma cells in vitro, probably through activation of JAk1/Stat1 pathway." (PMID 25428727, 2014). "Taken together, the present results suggest that IL-27 exerts anti-proliferative activity against human melanomas by mechanisms similar to those of IFN-α in a STAT1/IRF-1–dependent manner and partly in a TRAIL-dependent manner." (PMID 24155891, 2013). "Here we show that IFN-γ induces STAT1-dependently a profound up-regulation of the miR-29 primary cluster pri-29a~b-1 in melanoma cell lines." (PMID 23245396, 2012). "IFN signaling as determined by STAT1 phosphorylation was impaired in lymphocytes of patients suffering from breast cancer, melanoma, and gastrointestinal cancer." (PMID 22402907, 2012). "Paradoxically, others have proposed that STAT1 can facilitate tumor outgrowth since elevated levels of STAT1 in melanoma cell lines result in their acquisition of resistance to radiation or chemotherapy." (PMID 22264274, 2012). "Augmentation of IFN-alpha2b induced Stat1 tyrosine phosphorylation by SSG was also defined in WM9 human melanoma cells." (PMID 22201704, 2011). "Over-expression of SOCS proteins in melanoma cell lines led to significant inhibition of Tyr701-phosphorylated STAT1 (P-STAT1) and gene expression following stimulation with IFN-α (IFIT2, OAS-1, ISG-15) or IFN-γ (IRF1)." (PMID 20398276, 2010). "Recent studies from our group and others have demonstrated that the presence of constitutively active STAT3 in melanoma cells is correlated with reduced responsiveness to cytokines which act via STAT1 signal transduction." (PMID 20576164, 2010). "These investigators have used phospho-flow analyses for STAT1 phosphorylation to document a surprisingly high frequency of T cell signaling defects in the PB lymphocytes of patients with advanced melanoma (~30%)." (PMID 18954464, 2008). "Additionally, our previous research indicated that SHP1 competes with RIG‐I for binding to STAT1, thereby inhibiting STAT1 phosphorylation in melanoma." (PMID 40116486, 2025). "Notably, STAT1 was involved exclusively in Stage 4–specific synergistic relationships within the melanoma network, whereas TNFSF14, STK17B, SAMD3, PLAC8, and LYN were all Stage 1–specific synergistic genes that synergized with FENDRR." (PMID 40728857, 2025). "We therefore investigated whether the HH/GLI signaling pathway also contributes to IFNγ/STAT1 regulated IDO1 expression in melanoma." (PMID 39962447, 2025). "Notably, recent studies have demonstrated that type I interferons, which also activate the STAT1 pathway, can enhance the efficacy of anti-PD-1 therapies in melanoma." (PMID 41429766, 2025). "Collectively, these findings indicate that the absence of STAT1 is associated with the pro-tumor activity of N2 neutrophils and resistance to melanoma immune checkpoint inhibitors." (PMID 40226609, 2025).
melanoma (continued). "Additionally, it inhibited tumor growth in a B16F10 murine melanoma syngeneic model, accompanied by reduced STAT1 phosphorylation and decreased proliferation in Soman-treated mice, more potently than observed in Seoritae-treated mice." (PMID 40002413, 2025). "Similarly, simvastatin, a widely used HMG‐CoA reductase inhibitor, reduced melanoma resistance by inhibiting CIITA expression through STAT1 modulation." (PMID 41078003, 2025). "However, the observation that eIF4A inhibition counteracts the induction of PD-L1 by IFN-γ in melanoma, breast and colon cancer cell lines suggests the STAT1 RG4 to be a broad immunomodulator of PD-L1 expression in these cancer types." (PMID 38828391, 2024). "Cellular experiments validated the functional role of STAT1 in melanoma progression." (PMID 38770150, 2024). "Targeting genes like STAT1 could lead to the development of more effective treatments that directly impact melanoma cell behavior." (PMID 38770150, 2024). "Our data elucidates a mechanism by which IFNγ upregulates NAMPT in both human and mouse melanoma cells by inducing the signal transducer and activator of transcription 1 (STAT1) transactivation via a conserved enhancer that we recently identified in tumor-associated macrophages." (PMID 36900204, 2023). "Consequently, induction of PARP14 mRNA mirrored IFNG and STAT1 mRNA in on-treatment melanoma biopsies." (PMID 37752135, 2023). "Using phosphoflow cytometry to determine signaling response to IFN-γ, IFN-α, and IFN-β, phosphorylated STAT1 (p-STAT1) was reduced in lymphocytes stimulated only by IFN-α in melanoma patients compared to healthy controls, with these differences observed in CD8+ and CD4+ T cells, but not B cells." (PMID 37741983, 2023). "The overall survival rate of patients with high expressions of CCR7, CXCR5, EOMES, GBP4, TNFRSF9 and STAT1 in melanoma was significantly higher, which is consistent with the significantly higher survival rate observed for the young cohort receiving immunotherapy." (PMID 36135194, 2022). "Whole-exome sequencing of human melanoma tissues and the human melanoma cell line revealed that acquired resistance can result from loss-of-function mutations of IFNGR1, IFNGR2, JAK1, JAK2, STAT1, and IRF3 from the IFN-γ signaling pathway and β2M from antigen presentation pathway." (PMID 35432377, 2022). "Moreover, in melanoma, epigallocatechin gallate decreases PD-L1 expression by restraining STAT1 gene expression and phosphorylation followed by downregulation of IRF1 expression." (PMID 35907881, 2022). "A recently conducted study has shown that the ratio of phosphorylated STAT1 to STAT3 may be a biomarker that can predict the progression of melanoma." (PMID 35401182, 2022). "ARID2 was found to be a transcriptional repressor of STAT1 expression in melanoma cells and depletion of ARID2 enhanced the interferon γ response, resulting in increased STAT1 and STAT1 target gene expression, including PDL1 as well as several T cell chemokines." (PMID 35323214, 2022). "Surprisingly, we could not detect p-STAT1, even with a substantial amount of protein loading and prolonged film exposure times, indicating a low level of basal p-STAT1 in melanoma." (PMID 36008408, 2022). "Stat1 knockdown reduces the metastatic capacity of melanoma cells." (PMID 34685622, 2021). "Reduced migration and metastasis are detected in Stat1-knockdown melanoma cells." (PMID 34685622, 2021). "Furthermore, RET melanoma cells surrounded by CD8+ cells expressed a high level of p-STAT1, which was significantly increased within melanoma cells in the BGS-treated group." (PMID 34282238, 2021). "However, recent works have shown that Stat1 expression is dysregulated in cancers, including lung cancer, melanoma and Wilms’ tumor." (PMID 34685622, 2021). "Mechanistically, they revealed that TET2 could be recruited by STAT1 to hydroxymethylate the PD-L1 gene promoter and enhance its transcription in murine melanoma and colon tumor upon IFN-gamma stimulation." (PMID 34064441, 2021).
melanoma (continued). "Further, via the eIF4F-STAT1-PD-L1 axis, STAT1 could inhibit proliferation and induce apoptosis, thus blocking the growth of melanoma cells." (PMID 33511023, 2021). "Finally, RELA and STAT1 were selected as dual-input signals for a genetic biosensor in melanoma cells." (PMID 32712598, 2020). "Apart from STAT3, STAT1 has also been demonstrated to interfere melanoma development." (PMID 30166456, 2018). "However, another study showed that silencing STAT1 expression is a putative mechanism by which melanoma cells evade detection by immune cells, thereby allowing cancer proliferation." (PMID 30166456, 2018). "STAT1 is nitrated in the PBMC of melanoma and pancreatic cancer patients." (PMID 29133913, 2017). "STAT1 activation in response to IL-2 also showed an age-related decline in melanoma patients not linked to tumor burden indicating a premature loss of NK cell function." (PMID 27153543, 2016). "In a study of an IFN-γ-STAT1-miR-29 family interaction circuit, a minority of patient-derived primary melanomas were found to have markedly elevated miR-29b and miR-29a levels relative to benign nevi and normal skin, whilst metastatic samples had marginal or no elevation in miR-29a/b abundance." (PMID 27852308, 2016). "Silencing of STAT1 may be one mechanism by which melanoma can evade immune detection and, thus, increase its metastatic potential." (PMID 25690042, 2015). "Taken together with the present results, it is highly conceivable that IL-27–induced up-regulation of TRAIL in human melanomas could be also mediated by STAT1/IRF-1 signaling." (PMID 24155891, 2013). "In addition, we recently demonstrated that IL-27 has anti-proliferative activity and acts directly on melanomas through WSX-1/STAT1 signaling." (PMID 24155891, 2013). "Impaired IFN signaling may be rescued at the level of JAK-1 induced STAT1 phosphorylation; for example, by interleukin (IL)-12 pre-treatment, as was shown in a murine melanoma model." (PMID 22402907, 2012). "Since NF-kB and the IRFs are tightly involved in direct and indirect interactions, it is reasonable to postulate that the same mechanisms may be at the basis of the constitutive activation of STATs and in particular STAT-1 in melanoma." (PMID 21875439, 2011). "Highly invasive melanoma cell lines had high levels of STAT1 and c-myc." (PMID 21338529, 2011). "The expression of pyruvate kinase, HSP90 alpha, MIF, and STAT1 in primary and metastatic melanomas could be demonstrated by IHC staining." (PMID 19221597, 2009). "Thus, we assessed the effect of STAT1 blockage on anti-PD-1 efficacy in the context of B16-F10 melanoma-bearing mice, thereby elucidating whether STAT1 is associated with immunotherapy resistance." (PMID 40226609, 2025). "However, the function of aberrant STAT1 and the mechanism by which it causes melanoma are not yet fully understood." (PMID 37026000, 2023). "However, some studies have indicated that STAT1 participates in late-stage melanoma progression." (PMID 33511023, 2021). "For example, in the tumor microenvironment (TME), IFN-γ secreted by CD4+ and CD8+ T cells as an immune surveillance mechanism could upregulate PD-L1/PD-L2 in cancer cells, thereby contributing to tumor immune evasion via the IFN-γ-STAT1-PD-L1/L2 axis in melanoma." (PMID 34832863, 2021). "In addition, melanoma cells surrounded by CD8+ cells displayed augmented p-STAT1 signaling, which may be due to IFN-γ secretion by CD8+ cells within the tumor microenvironment." (PMID 34282238, 2021). "Moreover, the sustained activation of type I interferon signalling in response to IFNβ mediated by the Stat1/Stat2/IRF9 complex enhances the round amoeboid phenotype in melanoma cells, whereas its downregulation by various approaches promotes the mesenchymal invasive phenotype." (PMID 32872349, 2020).
melanoma (continued). "Thus, our results indicating significant basal activation of JAK2, SRC, STATs 1, 3, and 5, in melanoma aids in resolving finer aspects of STAT1 vs. STAT3 as well as acts as a springboard for dissecting studies on cytokine-induced STAT mediated cross-talks between JAK and SRC pathways." (PMID 28223541, 2017). "However, further study is warranted to analyse whether the defects of STAT1 signaling are observed in HD IL-2 treated melanoma patients who progressed from disease in comparison to patients who responded to IL-2 therapy." (PMID 27153543, 2016). "Additionally, we investigated whether IFNγ produced by IFNγ-ADSCs can activate the JAK/STAT1 dependent signaling pathway in melanoma cells." (PMID 25428727, 2014). "A final recent study upon STAT1 and T cell signaling in the blood lymphocytes of patients with melanoma is noteworthy, and may allow us to understand the treatment benefit of HDI, that has not been seen with other regimens of IFN that do not achieve high circulating levels of IFN in the blood." (PMID 18954464, 2008). "IFN-resistant melanoma cells contain reduced levels of ISGF3a components, particularly of STAT-1, indicating that the non-responsiveness of melanoma cell lines to type I IFN may be due to a deficiency in the expression of ISGF3 components." (PMID 17319941, 2007). "6-MF targets PTBP1 to inhibit circPIAS1 biogenesis and reduce circPIAS1-108aa.6-MF inhibits PI3K-AKT pathway; combined with IFN-γ, it enhances STAT1 phosphorylation, inhibits SLC7A11/GPX4 pathway, promoting melanoma ferroptosis." (PMID 41347180, 2025). "Network pharmacology analysis combined with experimental validation indicated that MBP exerts its anti-melanoma effects through multiple targets and pathways, prominently involving the JAK1/STAT1 signaling pathway." (PMID 40508400, 2025). "Five hub genes including CXCL11, ICAM1, LEF1, MITF, and STAT1 were identified, SUZ12, SOX2, TCF3, NANOG, and SMAD4 were determined as the most significant TFs in metastatic-melanoma." (PMID 39820173, 2025). "In melanoma, cytokines such as IFN-α/β can induce PD-1 expression directly on tumor cells via STAT1/2-mediated chromatin remodeling, highlighting the role of inflammatory signaling in enhancing PD-1 levels independently of T cell activation." (PMID 40869918, 2025). "When combined with IFN-γ, it significantly enhances STAT1 phosphorylation levels and inhibits the SLC7A11/GPX4 axis, thereby promoting ferroptosis in melanoma cells." (PMID 41347180, 2025). "In human melanoma cells, inhibition of GLI1 expression prevented the induction of IDO1 expression in response to IL6/STAT3 and IFNγ/STAT1 signaling." (PMID 39962447, 2025). "Using the UALCAN tool, we examined the association between hub gene expression and overall survival in melanoma and detected a substantial correlation among high levels of CXCL11, ICAM1 and STAT1 expression and poor prognosis." (PMID 39820173, 2025). "This inhibition occurs through a decrease in the expression and phosphorylation of STAT1, leading to reduced levels of IRF1, a key regulator of PD-L1 and PD-L2, in both human and murine melanoma cells." (PMID 40420174, 2025). "Previous studies have demonstrated that IFNγ-induced PD-L1 expression is reliant on JAK1/JAK2 activity, and that PD-L1 promoter activity and subsequent expression is mainly influenced by STAT1/STAT3 and IRF1 in IFNγ treated melanoma cells." (PMID 39736644, 2024). "Inhibition of the JAK kinases, NF-κB and STAT3 with small molecule inhibitors, and siRNA mediated knockdown of STAT1 and IRF1 was applied to investigate the molecular mechanism behind IFNγ induced PD-L1 expression in dedifferentiated melanoma cells." (PMID 39736644, 2024). "For instance, in melanoma cells, IFN-γ-mediated GILT protein induction occurs at a transcriptional level and is dependent on STAT1." (PMID 39273610, 2024).